IL10 (interleukin 10)
Diseases named in the same sentence as IL10 in open-access papers (continued):
Sharing a sentence is not in itself a finding about the gene and the disease.
calcification (2 papers, 2015 to 2020). Process by which organic tissue becomes hardened by the physiologic deposit of calcium salts. "After a multivariate adjustment, there was still a significant difference between the IL-10 gene polymorphisms and valvular calcification." (PMID 26039365, 2015). "The objective of this study was to investigate the association between valvular calcification and IL-10 genetic polymorphisms in the Han, Uygur and Kazak populations in China." (PMID 26039365, 2015). "In conclusion, polymorphisms of the IL-10 gene were associated with valvular calcification in the Kazak, Han and Uygur populations of western China." (PMID 26039365, 2015). "Twin studies and family studies have suggested that 75% of the variation in the production of IL-10 is determined by genes, and certain polymorphisms may alter the susceptibility to valvular calcification." (PMID 26039365, 2015). "Accordingly, the activity of IL-10 may be associated with the body’s susceptibility to valvular calcification." (PMID 26039365, 2015). "However, the relationship between IL-10 gene polymorphisms and valvular calcification remains unclear in the Han, Uygur and Kazak populations of western China." (PMID 26039365, 2015).
cardioembolic stroke (2 papers, 2015). "Since more women than men have cardioembolic strokes (men are more likely to have atherosclerotic events), this mirrors the IL-10 levels found in our cohort." (PMID 26462256, 2015).
cerebral palsy (2 papers, 2018 to 2020). A group of disorders affecting the development of movement and posture, often accompanied by disturbances of sensation, perception, cognition, and behavior. "Allele and genotype frequencies of IL-10 in total cerebral palsy (CP) patients and controls." (PMID 29623066, 2018). "Allele and genotype frequencies of IL-10 in cerebral palsy (CP) patient subgroups and controls." (PMID 29623066, 2018).
cerebral toxoplasmosis (2 papers, 2017 to 2019). Infections of the brain caused by the protozoan toxoplasma gondii that primarily arise in individuals with immunologic deficiency syndromes (see also aids-related opportunistic infections). "We previously showed that Ly6Chi monocytes express TNF and IL-10 in the CNS during cerebral toxoplasmosis." (PMID 28680853, 2017). "Together, these results demonstrate that increased parasite burden correlates inversely with the reduced levels of TNF, IFN-γ, IL-1 β, and IL-10 in brains of neutrophil-depleted mice with cerebral toxoplasmosis." (PMID 28680853, 2017).
Cholera (2 papers, 2015 to 2018). "Cholera toxin also suppresses production of IL-12 by bone marrow-derived DC, which drives Th1 responses 47, and induces production of IL-6 and IL-10 important in Th2 differentiation." (PMID 26130503, 2015).
chondrosarcoma (2 papers, 2019 to 2023). A malignant cartilaginous matrix-producing mesenchymal neoplasm arising from the bone and soft tissue. "Polarization of M2 macrophages leads to transcription of genes associated with the immunosuppressive macrophage phenotype in chondrosarcoma, including immunosuppressive markers such as arginase-1, TGF-β, and IL-10, as well as chemokines." (PMID 37993261, 2023).
chronic liver failure (2 papers, 2015 to 2025). Liver failure that develops slowly and gradually for some time, possibly for years, often as the result of cirrhosis, or malnutrition. "The elevated IL-10 has been previously implicated in the pathophysiological process of immune cell paralysis that characterizes the dysfunctional immune response in acute-on-chronic liver failure." (PMID 39889710, 2025).
chronic lung disease (2 papers, 2013 to 2024). According to the definitions of the American and British Thoracic Societies, including pulmonary functional tests, X-rays, and CT scans for items such as fibrosis, bronchiectasis, bullae, emphysema, nodular or lymphomatous abnormalities. "The overwhelming inflammatory response seen in mechanical ventilation, combined with the inability of type II epithelial cells to produce adequate IL-10 in response to mechanical stretch may be a critical component for the development of chronic lung disease." (PMID 23527226, 2013).
cleft lip (2 papers, 2021 to 2024). Congenital defect in the upper lip where the maxillary prominence fails to merge with the merged medial nasal prominences. "Our previous works revealed that a correlation between Ki 67 and cytokines IL-8 and IL-10 indicates the involvement of these cytokines in cell proliferation in cleft lip tissue." (PMID 34208325, 2021).
clonorchiasis (2 papers, 2020 to 2022). Infection of the biliary passages with clonorchis sinensis, also called Opisthorchis sinensis. "All these data suggested that IL-10 deficiency contributed to hepatobiliary injury in clonorchiasis." (PMID 36310865, 2022). "Our study supports that IL-10 plays a protective role in clonorchiasis via modulating Th17 cells’ response in C57/BL6J mice." (PMID 36310865, 2022). "IL-10, a cytokine with potent immune-regulatory capacity, its exact role in clonorchiasis is poorly understood." (PMID 36310865, 2022). "In our previous study, we showed dramatic changes of TLR2 and TLR4, and production of IFN-γ, IL-6, TNF-α, and IL-10 in the spleen were regulated by TLR4 as demonstrated in a murine model of clonorchiasis using TLR4 defective mice." (PMID 33489026, 2020). "Altogether, these results suggested that IL-10 deficiency promoted the recruitment and differentiation of Th17 cells but not Th1 and Treg cell subsets in clonorchiasis." (PMID 36310865, 2022). "However, the exact role of IL-10 in the complex immune response in clonorchiasis is poorly understood." (PMID 36310865, 2022). "Promoting IL-10 production might be a potential strategy to treat clonorchiasis." (PMID 36310865, 2022). "Taken together, our results suggest that IL-10 plays a protective role in hepatobiliary injury in C57BL/6J mice induced by C. sinensis infection via inhibiting Th17 cells, which could deepen our understanding of the immunopathology of clonorchiasis." (PMID 36310865, 2022).
colon adenocarcinoma (2 papers, 2020 to 2021). "IL-10 does not stimulate or affect IL-8 production by LPS or TNFα induced by human colon adenocarcinoma HT-29 cells, however Bifidobacterium sp." (PMID 33468130, 2021).
conjunctivitis (2 papers, 2019). Inflammation of the conjunctiva of the eye. "These paradoxical functions of IL-10 reinforce our observation of increasing tear IL-10 in patients when compared with control subjects, and at the same time, an inverted IL-10/TNF-α ratio, approximating to the Th2/Th9 mediated inflammation reported in experimental conjunctivitis." (PMID 30818819, 2019).
demyelinating peripheral neuropathy (2 papers, 2009 to 2012). "Overexpression of IL-10 in a transgenic mouse model leads to macrophage-mediated demyelinating polyneuropathy." (PMID 19771172, 2009). "Most often enhanced expression of IL-10 is beneficial for the individuals due to the activation of anti-inflammatory mechanisms, although a detrimental effect of IL-10 overexpression was demonstrated in a mouse model that subsequently developed a demyelinating peripheral neuropathy." (PMID 23062006, 2012).
diabetic macular edema (2 papers, 2015 to 2021). "Our results suggest that high levels of IL-1β, IL-6, and MCP-1 (proinflammatory and proangiogenic) and low levels of IL-10 (anti-inflammatory and anti-angiogenic) are involved in the pathogenesis of diabetic macular edema." (PMID 25923230, 2015).
dilatation (2 papers, 2018 to 2022). "IL-10 has been investigated as treatment for GI dilatation with variable efficacy." (PMID 30249047, 2018). "According to the presence or absence of bilateral ureteral dilatation, the AUCs for IL-10 and TNF-α were 0.813 (sensitivity 0.900 and specificity 0.625, p=0.026) and 0.950 (sensitivity 0.900 and specificity 0.875, p=0.001), respectively." (PMID 36524110, 2022). "Receiver operating characteristic (ROC) curves showed that IL-10 and TNF-α could distinguish bilateral ureteral dilatation in IRPF patients, with areas under the ROC curve (AUCs) of 0.813 (95% CI:0.607-1.000, p=0.026) and 0.950 (95% CI:0.856-1.000, p=0.001), respectively." (PMID 36524110, 2022). "Western blot analysis of the spleen, as well as ELISA for plasma protein, demonstrate reduced IL-10 protein levels in spleen and in circulating blood isolated from mice with GI dilatation, when compared to MHV-68-infected IFNγR−/− mice without GI dilatation (p = 0.0385)." (PMID 30249047, 2018).
diverticulitis (2 papers, 2022). An infection that develops in the diverticula of the intestinal tract. "The results showed that IL-10 release was significantly increased in SUDD patients with previous acute diverticulitis compared to asymptomatic subjects probably as a counter-regulatory signal of increased pro-inflammatory cytokines." (PMID 35743141, 2022). "Moreover, interleukin-10 (IL-10), a potent anti-inflammatory regulatory cytokine, is significantly decreased in active IBD, does not decrease in SUDD, and is moreover increased in post-diverticulitis SUDD." (PMID 36499127, 2022).
Dysmenorrhea (2 papers, 2017 to 2025). Pain during menstruation that interferes with daily activities. "SFZYD has also been shown to effectively treat dysmenorrhea, a primary symptom of blood stasis, by regulating the expression of inflammatory cytokines, such as IL-1β, TNF-α, IL-10, IL-2 and IL-12, in a rat model." (PMID 28570676, 2017).
eosinophilic esophagitis (2 papers, 2024 to 2025). Eosinophilic esophagitis (EoE) is a chronic, allergic disease of the esophagus characterized clinically by symptoms of esophageal dysfunction (including vomiting, dysphagia, feeding disorders, food impaction and abdominal pain) which persist after treatment with proton pump inhibitors (PPIs). "Notably, in eosinophilic esophagitis (EoE), a type 2 inflammation-driven disorder triggered by food proteins, milk-responsive Tfh cells, which produce IL-10 and low levels of IL-4, support class switch to IgG4 and contribute to distinct clinical manifestations." (PMID 40574856, 2025).
Epidermolysis bullosa acquisita (2 papers, 2022 to 2024). "More recent experimental evidence in a mouse model of epidermolysis bullosa acquisita would confirm the immunomodulatory role of vitamin D via increase of CD4+ forkhead box P3 (FoxP3)+ Tregs and B cells (CD19 + IL10+), concomitant with the reduction of proinflammatory Th17 cells." (PMID 39796035, 2024). "In a mouse model for the autoimmune skin blistering disease Epidermolysis bullosa acquisita (EBA), IL-10 blockade has been shown to largely downregulated disease pathogenicity by inhibiting innate effector functions, while induction of IL-10+ plasma cells could inhibit the disease." (PMID 35979356, 2022).
fibroids (2 papers, 2021 to 2023). "The decrease of TGFβ, IL6, and IL10 immunoexpression, as well as the macrophage and mast cell infiltration in fibroids, observed in cases of a good response to the UPA treatment may be an important component of the total effect of UPA on uterine fibroid tissue." (PMID 34442017, 2021). "Numerous studies described leiomyoma cells exhibiting a significantly greater expression of IL1, IL4, IL5, IL6, IL10, IL11, IL13, and IL15." (PMID 34442017, 2021).
folate deficiency (2 papers, 2023 to 2025). A nutritional condition produced by a deficiency of FOLIC ACID in the diet. "It has been reported that folate deficiency further aggravates skin inflammation and suppresses the secretion of the anti-inflammatory cytokine IL-10." (PMID 39919369, 2025). "The NF−f mice had the lowest renal IL-10 among the dietary groups due to an interaction between the effects of folate deficiency and HFF." (PMID 37630806, 2023).
foot and mouth disease (2 papers, 2020 to 2025). A viral infectious disease that results in infection in cattle and swine, has material basis in foot-and-mouth disease virus, which is transmitted by contaminated fomites, or transmitted by ingestion of food contaminated with infected meat or animal products. "(2009) showed that IFNγ, IL-10, and TNFa had peaked on week 3 in response to inactivated foot-and-mouth disease (FMD) vaccination while the remaining cytokines (IL-2, IL-4, IL-12p40) peaked on the 2nd week and decreased by the 3rd week." (PMID 33251155, 2020). "Early-infection work in bovine foot-and-mouth disease reported IL-10 as optical density units rather than pg/mL, illustrating how reporting format can hinder quantitative benchmarking against our SPRi data." (PMID 41226434, 2025).
gastrointestinal stromal tumor (2 papers, 2015 to 2021). "Administration of imatinib after agonistic anti-CD40 antibody activated TAMs, redirected TAMs to antitumor M1 phenotype, by increased TNF and IL-6 production through the NFκB pathway along with decreased IL-10 production in mouse model of gastrointestinal stromal tumor GIST." (PMID 34209679, 2021).
gynecologic cancers (2 papers, 2023). "In gynecological cancers, a high concentration of TAMs and Tregs is associated with worse survival, and the secretion of IL-10 by TAMs regulates the activation of Treg lymphocytes." (PMID 37048119, 2023). "Compared to patients with non-gynecologic cancers, more patients with gynecologic cancers express high levels of IDO-1 (44 vs. 13%, p<0.001), LAG3 (35 vs. 21%, p=0.008) and IL10 (31 vs. 15%, p=0.002)." (PMID 36824739, 2023).
HELLP syndrome (2 papers, 2022). A life-threatening condition that can potentially complicate pregnancy. "A recent systematic review shows evidence that sFlt-1, PlGF, IL-6, IL-6/IL-10 ratios are interesting candidate biomarkers for cardiovascular risk stratification after PE or HELLP syndrome (hemolysis, elevated liver enzymes and low platelets)." (PMID 35883900, 2022).
Hernia (2 papers, 2023 to 2024). "Hernia surgery was shown to increase CRP, IL-6 levels, leukocyte count, neutrophil count, IL-1 levels, IL-10 levels, fibrinogen, and α1-antitrypsin, and decrease lymphocyte counts and albumin during the first 24 postoperative hours." (PMID 36739352, 2023).
herpetic keratitis (2 papers, 2017 to 2020). "The beneficial effect of IL-10 in ocular diseases have been shown in promoting corneal transplant survival, and in herpetic keratitis models including IL-10 deficient mice." (PMID 32586018, 2020). "Indeed, overexpression of IL-10 was beneficial in treatment of ocular inflammatory diseases such as herpetic keratitis." (PMID 29158874, 2017).
Huntington disease (2 papers, 2017 to 2022). Huntington disease (HD) is a rare neurodegenerative disorder of the central nervous system characterized by unwanted choreatic movements, behavioral and psychiatric disturbances and dementia. "In accordance, a recent report demonstrated that Galectin-3 KO in the brains of Huntington’s disease model R6/2 mice significantly upregulated expression of IL-10 in striatal lysates." (PMID 36076283, 2022).
hypersensitivity reactions (2 papers, 2015 to 2022). "Th2 cells produce IL-4, IL-5, IL-6, and IL-10, mediate humoral immunity, and are closely associated with the development of hypersensitivity reactions." (PMID 35419003, 2022). "Skin sensitization is primary associated with induction of Th1 cells, promoting a cytotoxic CD8+ T-cell response and secretion of IL-2 and interferon (IFN)-γ, while respiratory sensitization generally involve CD4+ Th2 cells and are characterized by high levels of IL-4, IL-10 and IL-13." (PMID 25760038, 2015).
hypertrophic cardiomyopathy (2 papers, 2024 to 2025). A condition in which the myocardium is hypertrophied without an obvious cause. "Studies indicate elevated levels of cytokines like TNF-α, hs-CRP, and inflammatory interleukins (e.g., IL-1β, IL-1RA, IL-6, IL-10, circulating monocyte chemoattractant protein resulted in a chronic low-grade inflammatory state in hypertrophic cardiomyopathy (HCM)." (PMID 38533084, 2024).
Hypovitaminosis (2 papers, 2019 to 2025). "Hypovitaminosis D then favours the overexpression of Th1 cytokines and inhibits the production of anti-inflammatory cytokines such as IL-10." (PMID 30998727, 2019). "The median circulating IL-10 levels were compared between individuals with vitamin deficiency and non-deficient patients." (PMID 40630332, 2025).
IgA deficiency (2 papers, 2021 to 2023). "Any deficiency or polymorphisms in IL-10 or reduction in the number or activity of Tregs might thus contribute to the development of IgA deficiency." (PMID 33981304, 2021).
inflammatory bone disease (2 papers, 2018 to 2019). "The combination of vancomycin treatment and HBO therapy did not lead to a significant reduction of the bacterial load, the histo-pathologically evaluated degree of osteitis and IL-1b, IL-10, and TNF-a levels, in comparison to vancomycin treatment alone." (PMID 29377928, 2018). "IL-10 is a well-known anti-inflammatory cytokine, and decreased IL-10 levels contribute to pathological development in both IBD and inflammatory bone disease." (PMID 31847438, 2019).
internalizing disorder (2 papers, 2021 to 2022). A type of mental or behavioral disorder, typically in children and young adults, with symptoms including depression, anxiety and withdrawal. "Interestingly, two studies have reported increased IL-10 in pediatric internalizing disorders compared to controls under basal conditions." (PMID 35880170, 2022).
intestinal amebiasis (2 papers, 2022 to 2024). "A study by Hamano has shown that IL-10 is required for resistance to intestinal amebiasis and that IL-10 deficiency leads to high susceptibility to amebic infection in mice." (PMID 36678367, 2022). "IL-10 is an additional cytokine with a central protective role during intestinal amoebiasis by triggering resistance to intestinal amoebiasis in B6 mice." (PMID 38623843, 2024).
Intraventricular hemorrhage (2 papers, 2020 to 2025). Bleeding into the ventricles of the brain. "Interestingly, patients with intraventricular hemorrhage or a combined IVH and ICB had higher IL-10 levels on admission, showing the influence of IVH in the brain, i.e., that it may control systemic IL-10 release through brain–immune-system interactions." (PMID 32106601, 2020). "Serum IL-10 levels were significantly higher on day 1 post-SAH in patients with intracerebral bleeding (ICB) only when this complication was accompanied by intraventricular hemorrhage (IVH); ICB alone did not change the serum IL-10 levels." (PMID 32106601, 2020).
ischemic disease (2 papers, 2013 to 2019). Lack of blood supply to an area of the body, resulting in impairment of tissue oxygenation. "TNF-α and IL-10 are known to be pro- or anti-inflammatory cytokines in ischemic diseases and its animal models." (PMID 31419236, 2019). "Although the sequence of chemical base pairs and most SNPs of the IL-10 gene have been identified, their role in the aetiology of ischemic disease in humans is still largely unknown." (PMID 24040186, 2013).
juvenile dermatomyositis (2 papers, 2015 to 2022). Juvenile dermatomyositis (JDM) is the early-onset form of dermatomyositis (DM), a systemic, autoimmune inflammatory muscle disorder, characterized by proximal muscle weakness, evocative skin lesion, and systemic manifestations. "In addition, HSP60 (10 μg/ml) has been reported to induce significant amounts of TNF-α, IL-1 and IL-10 from peripheral blood mononuclear cells of patients with juvenile dermatomyositis." (PMID 25915936, 2015).
Kaposi's sarcoma (2 papers, 2010 to 2025). A malignant neoplasm characterized by a vascular proliferation which usually contains blunt endothelial cells. "In the IRIS patient that presented with Kaposi's sarcoma, increases in IL-6, IL-10, IL-12, IL-13 and IFN-γ expression were shown." (PMID 20929543, 2010).
kidney stones (2 papers, 2020 to 2022). "The aim of this study was to investigate the effects of SWL, for the treatment of kidney stones, on routine blood tests, and specific biomarkers, namely NGAL, IL-18, IL-6, IL-10 and IL-8." (PMID 32487191, 2020).